RNU6-465P (RNA, U6 small nuclear 465, pseudogene)
Gene: Small nuclear RNA gene on chromosome 1 (120,126,974 to 120,127,074, forward strand). Ensembl gene ENSG00000207149.
Homologues: Orthologues: chimpanzee U6 (99% identical), macaque U6 (96% identical), guinea pig U6 (83% identical), rat LOC120096740 (82% identical), pig U6 (76% identical), pig U6 (69% identical). Paralogues in human: RNU6-1071P (100% identical), RNU6-1171P (100% identical), RNU6-1042P (91% identical), RNU6-891P (91% identical), RNU6-15P (90% identical), RNU6-698P (90% identical), RNU6-831P (90% identical), RNU6-1060P (89% identical), RNU6-1145P (89% identical), RNU6-116P (89% identical), RNU6-166P (89% identical), RNU6-25P (89% identical), and 1288 more.